EGFR (epidermal growth factor receptor)
Diseases named in the same sentence as EGFR in open-access papers (continued):
Sharing a sentence is not in itself a finding about the gene and the disease.
lung cancer (continued). "Among lung cancer patients with EGFR sensitizing mutations and on therapy, CSF sequencing demonstrated the emergence of gatekeeper mutations associated with acquired resistance, including EGFR p.T790M, p.C797S, p.L792H, p.L718Q, p.L718V and p.G724S." (PMID 39289779, 2024). "Moreover, lung cancers harboring EGFR mutations exhibit increased resistance to tyrosine kinase inhibitors (TKIs) such as Erlotinib and Gefitinib when NF1 levels are low." (PMID 39596025, 2024). "This study showed whether the ODxTT and AmoyDx panel could detect EGFR mutations from a real-world specimen from patients with lung cancer." (PMID 38238401, 2024). "Since our hospital is the largest cancer center in Taiwan and conducting multiple clinical trials of lung cancer, this high EGFR mutation rate may be due to referred cases from other hospitals after diagnosis or disease progression." (PMID 38687753, 2024). "Additionally, HHLA2 expression was found to be elevated in lung cancer with EGFR mutation—one of the most common mutations in lung cancer." (PMID 38786018, 2024). "Secondly, the lung cancer cells employed in this study harbor specific EGFR mutations (del 19 or L858R/T790M), which could potentially bias the results." (PMID 39766891, 2024). "Similarly, in lung cancer, the detection of EGFR mutations in CTCs can guide the use of EGFR inhibitors." (PMID 38611055, 2024). "Interestingly, following treatment with erlotinib in combination with the WT1/MUC1-DC vaccine, the tumor was undetectable by CT analysis for at least 587 days after treatment in a patient with lung cancer with EGFR-mutated adenocarcinoma." (PMID 38336778, 2024). "In contrast, the OS tended to be shorter in patients with minor EGFR mutations, but without statistical significance (median: 62.7 vs. 35.1 months, p = 0.636), again suggesting that the importance of EGFR-TKI duration for survival benefit in EGFR-mutated lung cancer." (PMID 38347279, 2024). "There is a significant association between EGFR mutation and the risk of BMs at the time of initial diagnosis in advanced lung cancer, and there is a high adjusted odds ratio (3.83) between EGFR mutation and the risk of BMs at the time of follow-up after curative resection for LUAD 4,5." (PMID 38464823, 2024). "The ability of fusion proteins to facilitate EGFR ubiquitination and subsequent degradation provides a novel strategy for reducing EGFR signaling, which is a key process implicated in the growth and progression of lung cancer." (PMID 39130630, 2024). "Importantly, these findings broadly applied to lung cancers with various RTK/MAPK pathway alterations — including EGFR mutations, ALK fusions, or KRASG12C mutations." (PMID 38483480, 2024). "It is also associated with EGFR-TKI resistance in lung cancer." (PMID 39324002, 2024). "Representative drugs that target EGFR mutations in lung cancer." (PMID 38474400, 2024). "Additionally, studies have shown that PTEN loss results in sustained Akt and EGFR activation, providing a survival advantage and potential resistance to EGFR inhibitors in lung cancer cells." (PMID 38877005, 2024). "In our study, 80.7% of patients were diagnosed with stage III-IV lung cancer, and EGFR mutation status was incorporated into the multivariate analysis and identified as an independent prognostic factor for patients with lung cancer and ILA, after excluding those with subpleural fibrotic ILA." (PMID 38783331, 2024). "Specifically, troglitazone could synergize with cisplatin or paclitaxel to inhibit NSCLC both in vitro and in vivo in a sequence-specific manner, while rosiglitazone combination with carboplatin reduced the growth of KRAS- or EGFR-mutated lung cancers." (PMID 38397426, 2024). "However, no reports have investigated the extent to which these two CDx tests cover EGFR mutations in lung cancer specimens." (PMID 38238401, 2024).
lung cancer (continued). "However there was a modestly increased prevalence of EGFR indel mutations in individuals diagnosed with lung cancer before age 50, which reached statistical significance in the combined analysis." (PMID 39052387, 2024). "Oral inhibitors of the EGFR oncogene are approved for use in EGFR mutated lung cancers." (PMID 38539415, 2024). "However, as for early-stage lung cancer, the disparities in clinical features and survival outcomes due to the EGFR mutations had already generated." (PMID 38528507, 2024). "The study included 70 consecutive patients with advanced-stage lung cancer, and aimed to identify common EGFR mutations (Exon 19 deletion and Exon 21 L858R mutation), determine their frequency, and correlate EGFR-TK mutation positivity with clinical and non-clinical factors." (PMID 39429333, 2024). "Lung cancers with EGFR mutations mostly presented with an early TNM stage (p = 0.034)." (PMID 38783331, 2024). "Variants in EGFR have been identified in connection with certain types of lung cancers." (PMID 38245692, 2024). "The marginally higher proportion of these EGFR variants in FFPE samples might be attributed to variations in histological subtypes of lung cancer." (PMID 39231944, 2024). "Extensive work is being performed in the field utilizing biosensors for lung cancer detection, including the detection of analytes such as circulating tumor nucleic acids including Epidermal Growth Factor Receptor (EGFR) and KRAS mutations, microRNA, and specific proteins such as CEA." (PMID 38841615, 2024). "Furthermore, in vitro studies in lung cancer cells showed that EGFR exon 19 mutations increase DPD expression through the transcriptional factor SP1." (PMID 38248103, 2024). "This implies that germline risk variants such as PGVs could be the link between ethnicity and risk for EGFR-mutant lung cancer." (PMID 38539485, 2024). "Additionally, the review assesses osimertinib’s safety and efficacy in patients with early-stage EGFR-mutated lung cancer, drawing from a wide range of studies and clinical trials." (PMID 39624538, 2024). "The purpose of this paper is to present the study protocol and results of a validation substudy for a planned retrospective cohort study of the safety and effectiveness of erlotinib and gefitinib during the first decade of their use in NZ for treating advanced EGFR mutation–positive lung cancer." (PMID 38954434, 2024). "The combination of genistein with other compounds is effective against non-small cell lung cancer (NSCLC) cell lines by targeting mutated EGFR, showing a synergistic anticancer effect; however, the exact role of genistein in lung cancer remains unclear." (PMID 38731403, 2024). "The treatment of advanced lung cancer has been revolutionised in recent years, with the identification of immunotherapy and targeted agents acting on various molecular drivers like the epidermal growth factor receptor (EGFR) mutations." (PMID 39021550, 2024). "Notably, in two patients (8.0%) with lung cancer, EGFR mutations (p.E709_T710delinsD and p.L861R) were newly detected, and they received osimertinib, an EGFR tyrosine kinase inhibitor (TKI)." (PMID 38668785, 2024). "Based on the clinical guidelines outlined by the National Comprehensive Cancer Network (NCCN) for the treatment of lung cancer, patients with tumors harboring activating mutations in the epidermal growth factor receptor (EGFR) gene require therapy with tyrosine kinase inhibitors (TKIs)." (PMID 39001552, 2024). "However, lung cancer patients, who have mutations in the EGFR gene, are sensitive to tyrosine kinase inhibitors (TKIs) drugs." (PMID 38234663, 2024).
lung cancer (continued). "Furthermore, the ADAURA study recently reported that adjuvant osimertinib therapy to patients with completely resected lung cancer harboring EGFR mutation provided a significant overall survival benefit." (PMID 38323355, 2024). "Multiple EGFR germline mutations have been identified in lung cancer patients, but the optimal treatment regimen for lung cancer with EGFR germline mutations is unknown." (PMID 39160638, 2024). "Among 140 lung cancer patients, 46 had EGFR mutations, yielding a mutation rate of 33%." (PMID 39735556, 2024). "EGFRvIII is a variant of EGFR that is particularly common in lung cancer." (PMID 38886844, 2024). "In a previous study conducted by the University of California Lung Cancer Consortium, 54.9% of patients had EGFR mutations, 32.9% of patients had KRAS mutations, 5.3% of patients had ALK fusions, and < 3% of patients had other mutations (HER2, MET, RET, ROS1, or BRAF-non-V600E)." (PMID 39009968, 2024). "Notably, young lung cancer patients often harbor a higher frequency of driver mutations, including epidermal growth factor receptor (EGFR) and anaplastic lymphoma kinase (ALK) translocations." (PMID 38946288, 2024). "EGFR mutations are frequent in glioblastoma and lung cancer." (PMID 38548752, 2024). "We found that a case with EGFR 19del mutation had focal malignant features, suggesting that this tumor may be a prodromal stage in the development of lung carcinoma, but this hypothesis needs to be confirmed with more cases." (PMID 38902753, 2024). "The majority of lung cancers (about 85%) are non-small cell lung cancer (NSCLC), and epidermal growth factor receptor (EGFR) mutations are the most frequent driver mutation in lung cancer, occur in around 50% of Asia-Pacific patients with NSCLC and 15% of Western patients." (PMID 36875137, 2023). "Moreover, EMT is capable of conferring resistance towards epidermal growth factor receptor (EGFR) blockade in lung cancer and is linked to the induction of the receptor tyrosine kinase (RTK) Axl in HCC." (PMID 37746265, 2023). "Many mutation sites of EGFR have been determined to be involved in lung cancer formation." (PMID 36918558, 2023). "One review of lung cancer management in South Africa noted that for private sector patients with EGFR mutations, only erlotinib is available for first line use, osimertinib is available in the second line setting and crizotinib is the only drug available for ALK positive patients." (PMID 37368872, 2023). "In addition, HER3 overexpression has been observed in EGFR-mutated lung cancer models treated with osimertinib." (PMID 37894376, 2023). "Our recent published studies demonstrate that EGFR-targeted inhibitors induce an interferon (IFN) response program that varies markedly between distinct EGFR mutant lung cancer cell lines and positively associates with the duration of therapeutic response in EGFR-mutant lung cancer patients." (PMID 36739466, 2023). "Longitudinal molecular testing is crucial for EGFR-mutated lung cancer, and the optimal technique may involve NGS or targeted approaches." (PMID 37713929, 2023). "The relationship between EGFR mutation and metabolic activity of lung cancer has been evaluated." (PMID 37014455, 2023). "Furthermore, the study also extended its investigation to animal models by xenografting lung cancer cells that expressed the EGFR T790M mutation, providing additional evidence supporting the potential efficacy of UA in treating this specific subtype of NSCLC." (PMID 38067626, 2023). "Subgroup analysis showed that the HR was even better in stage I–II patients (P < 0.0001; HR, 0.1003; 95% CI, 0.0236–0.427), and that the discriminatory ability was effective for both EGFR wild-type lung cancer and lung cancer harboring activating EGFR mutations." (PMID 37476074, 2023).
lung cancer (continued). "The final model comprised 15 predictors, namely age, KPS, NSE, PLR, lymphocyte count, ALP, smoking history, intrathoracic metastasis, metastases to other sites, N_stage, M_stage, surgery for primary lung cancer foci, chemotherapy EGFR mutation, and TKI treatment." (PMID 37456882, 2023). "The first breakthrough in identifying a population of lung cancer patients likely to respond to molecularly targeted therapy was made in 2004 with the identification of EGFR activating mutations, and since then the field of individualized lung cancer drug use has grown rapidly." (PMID 37695388, 2023). "Therefore, we studied the effect of EGFR-TKIs resistance on the growth and metastasis of lung cancer cells associated with DNA methylation." (PMID 36778111, 2023). "Furthermore, lung cancers with EGFR mutation which acquired resistance to EGFR tyrosine kinase inhibitors (EGFR-TKIs) are found to be sensitive to ferroptosis mediated cell death." (PMID 36926345, 2023). "In addition, Tian and his colleagues incorporated radiomics features to build prediction model for the epidermal growth factor receptor (EGFR) mutation status in lung cancer." (PMID 37964254, 2023). "However, limited studies have been reported about the EGFR mutation distribution across different regions of lung cancer patients." (PMID 37767514, 2023). "This study included a total of 89 patients aged ≥75 years who were diagnosed with EGFR mutation-positive, nonsmall cell lung cancer and treated with EGFR-TKIs at the Tokyo Metropolitan Geriatric Hospital and Nihon University ITABASHI Hospital from 2009 to 2020." (PMID 37179737, 2023). "Similarly, weekly intermittent “pulses” of high‐dose erlotinib (1500 mg) resulted in CSF concentrations above half‐maximal inhibitory concentrations against lung cancer cells with EGFR mutations in patients with leptomeningeal metastases." (PMID 37691552, 2023). "ASTRIS study aimed the largest to evaluate the effectiveness and safety of second- or higher-line osimertinib in patients with advanced/metastatic epidermal growth factor receptor (EGFR) T790M mutation-positive non–small cell lung cancer (NSCLC) in the real-world setting." (PMID 37316692, 2023). "High APOBEC3B expression has been associated with poor response to Raf inhibitors in glioma, and certain APOBEC3-induced mutations may predict resistance to Raf inhibitors and EGFR inhibitors in multiple myeloma and lung cancer, respectively." (PMID 36978147, 2023). "The prediction model comprised 15 variables, including age, KPS, NSE, PLR, lymphocyte count, ALP, smoking history, intrathoracic metastasis, metastases to other sites, N_stage, M_stage, surgery for primary lung cancer foci, chemotherapy, EGFR mutation, and TKI treatment." (PMID 37456882, 2023). "We previously reported that the lung cancer compact panel TM (LCCP) could detect EGFR and MET gene mutations with sputum cytology." (PMID 37510070, 2023). "Real-world survival outcomes of patients with EGFR-mutated lung cancer may be superior with a sequenced TKI strategy." (PMID 37198447, 2023). "EGFR-activating mutations was most common in patients with lung cancer, especially LUAD." (PMID 37576883, 2023). "In addition, new biomarkers are needed to differentiate patients with EGFR mutation-positive lung cancer who are resistant to EGFR-TKIs." (PMID 36910653, 2023). "Moreover, GAB1 is associated with HGF-stimulated VEGF production in EGFR-mutant lung cancer cell lines." (PMID 37627207, 2023). "To explore whether GEMINI could be used to monitor patients during therapy, we assessed serial blood samples from patients with lung cancer who were undergoing treatment with EGFR or ERBB2 inhibitors with mutant allele fractions (MAFs) as low as 0.1%." (PMID 37500728, 2023). "Air pollution, lung cancer incidence and EGFR mutation status could be estimated for 20 Cancer Alliance regions in England." (PMID 37020004, 2023).
lung cancer (continued). "Lung cancer patients with ALK-rearrangement or EGFR mutations showed a poor response to ICIs." (PMID 36874015, 2023). "For example, a large proportion of lung cancers carry mutations in the EGFR, ALK, and KRAS genes." (PMID 37631277, 2023). "In several human cancers, including glioblastoma, colorectal cancer, breast cancer, and lung cancer, the EGFR gene is often amplified and mutated and the EGFR protein is overexpressed, leading to chronic receptor activation, excessive signaling, and the promotion of neoplastic transformation." (PMID 37446908, 2023). "Previous reports showed that NTRK fusion might be the acquired resistant variant for the EGFR TKI in lung cancer patients." (PMID 37567953, 2023). "Notably, Yunnan is a regional high incidence area of lung cancer in the highlands with a high rate of rare EGFR mutations." (PMID 37881485, 2023). "Therefore, in the future, the EFIRM platform’s electrochemical detection method combined with microarray technology can offer significant benefits for EGFR mutation monitoring in lung cancer patients." (PMID 37373532, 2023). "Whether micro T790M detected by NGS can help in the selection of treatment for EGFR mutated lung cancer needs to be further investigated." (PMID 37957228, 2023). "Decisions about targeted therapy, such as choosing certain tyrosine kinase inhibitors for individuals with epidermal growth factor receptor (EGFR) or anaplastic lymphoma kinase (ALK) mutations in lung cancer mutations, might be aided by ctDNA analysis." (PMID 37719630, 2023). "The confirmation of the correlation between tumor volume reduction and IC50 value suggests that this approach may serve as a predictive tool for the efficacy of targeted agents in treating EGFR mutations-associated lung cancers." (PMID 37941550, 2023). "Temporal analysis suggested that 3 years of PM2.5 exposure may be sufficient to increase the risk of developing EGFR-driven lung cancer." (PMID 37020004, 2023). "The proportion of EGFR mutations was markedly higher than in previous studies (235/1521, 15%), which may be due to a trend specific to Asian ancestry patient lung cancers." (PMID 36750899, 2023). "Although PD-1/PD-L1 inhibitors have shown promising results in lung cancer, they may be limited in patients with EGFR mutations." (PMID 37345194, 2023). "The progressive better understanding of EGFR mutations in mNSCLC has allowed to set up the Lung Cancer Molecular Markers Graded Prognostic Assessment (Lung-mol-GPA based on EGFR status as the main target combined with other clinical parameters to help clinical decisions on newly diagnosed with BM." (PMID 36786970, 2023). "EGFR alterations (mutations, amplification) are commonly seen in lung cancer cells." (PMID 37919290, 2023). "This two-center, retrospective study was conducted to determine which EGFR-TKIs could be appropriate for older patients with EGFR mutation-positive, nonsmall cell lung cancer based on safety and efficacy." (PMID 37179737, 2023). "In addition, tyrosine kinase phosphorylation is mediated by EGFR mutation, which in turn activates NF‐κB, resulting in PD‐L1 overexpression in lung cancer." (PMID 36515567, 2023). "Chen’s study demonstrated that MR imaging based radiomic analysis of BM in patients with primary lung cancer may be used to classify EGFR, ALK, and KRAS mutation status and the AUC values based on cross validation was 0.912, 0.915, and 0.985, respectively." (PMID 38027000, 2023). "To understand whether AICAR’s effects are dependent upon EGFR mutations, we tested drug response in another panel of lung cancer cells with wild-type EGFR, including H358, H23, H441, A549, and H69." (PMID 36810913, 2023).